PRSS29P (serine protease 29, pseudogene)
Synonyms: ISP2
Gene: Transcribed unprocessed pseudogene on chromosome 16 (1,261,313 to 1,263,212, reverse strand). Ensembl gene ENSG00000196364.
Subcellular location: Secreted